INS (insulin)
Diseases named in the same sentence as INS in open-access papers (continued):
Sharing a sentence is not in itself a finding about the gene and the disease.
diabetes (continued). "Of the 26 women with preexisting diabetes, all were diagnosed before 29 years of age, 19 were treated with insulin, 2 with other drugs, and 4 with diet only." (PMID 22927834, 2012). "Pancreatic β-cells, insulin signaling and the contribution to diabetes and the balance of hematopoietic cells in immunity are the main examples that were illustrated in this review." (PMID 22680924, 2012). "The pancreas, which secretes two key glucose-regulating hormones—insulin and glucagon—is an important organ in diabetes mellitus." (PMID 22337138, 2012). "Basic criteria for WS clinical diagnosis were coexistence of insulin-treated diabetes mellitus and optic atrophy occurring before 15 years of age." (PMID 22238590, 2012). "Type 2 diabetes mellitus is characterized by persistent hyperglycemia resulting from defect of insulin secretion and insulin action." (PMID 22701507, 2012). "This has been supported by the Diabetes Mellitus, Insulin Glucose Infusion in Acute Myocardial Infarction (DIGAMI) trial." (PMID 22347666, 2012). "Diabetes mellitus type 2 (DM2) occurs when the β-cells of the pancreas cannot secrete sufficient amounts of insulin to meet the metabolic demand generated by the resistance to the effect of insulin in tissues such as muscle, liver and adipose tissue." (PMID 24893199, 2012). "The structured questionnaire was prepared in a context of a mobile diabetes monitoring system that controls blood glucose, weight, physical activity, diet, insulin and medication, and blood pressure." (PMID 23257115, 2012). "In a population-based case–control study of PanCa, participants with PanCa were more likely to report a history of diabetes (13%) and had a shorter duration of diabetes and a larger proportion of insulin users than the control groups." (PMID 22920886, 2012). "Biologic modules comprised of up-regulated genes in response to SF included “mitochondrion and oxidative phosphorylation”, “insulin regulation and diabetes pathways”, “lipoprotein biosynthesis and protein lipidation” and “proteasome pathways”." (PMID 22629440, 2012). "In fact, among the continuous parameters, the strongest predictors of diabetes development were glycemic levels, BMI, insulin sensitivity expressed by OGIS (P<0.0001 for all variables)." (PMID 23185618, 2012). "To further elucidate relationships among members of gene sets, we constructed a gene product interaction network, or interactome, for the “insulin regulation and diabetes” module." (PMID 22629440, 2012). "Diabetes mellitus (DM) is a group of metabolic diseases which is characterized by the high levels of blood glucose resulted from defects in insulin secretion, insulin action, or both." (PMID 22721433, 2012). "The mean capillary ATP concentrations in the absence and presence of insulin are 0.076 and 0.038 μM, respectively, implying a 50% decrease when plasma insulin is increased to values found in pre-diabetes." (PMID 22934004, 2012). "Diets based on foods that produce lower postprandial blood glucose responses (i.e. LGI foods) reduce the risk of developing diabetes, CVD and certain cancers while improving insulin sensitivity, blood glucose control and blood lipid profiles." (PMID 22780564, 2012). "The remaining question to be answered is to explore factors in blood that are necessary to sensitize the responses of α-cell to hypoglycemia and the mechanism of the potential sensitization of α-cells to insulin in diabetes." (PMID 22969729, 2012). "Patients should be informed early on about the natural progression of diabetes and the need for insulin therapy 10–15 years after the diagnosis." (PMID 22469132, 2012). "Diabetes mellitus is a metabolic disorder that results from a reduction of insulin available for normal function of many cells in the body." (PMID 22844268, 2012). "Sulphonylureas like tolbutamide have been used to enhance insulin secretion in patients with type II (non-insulin-dependent) diabetes mellitus." (PMID 23056144, 2012).
diabetes (continued). "Insulin-Dependent Diabetes Mellitus (IDDM) is commonly known as Type 1 diabetes mellitus, which is a consequence of autoimmune destruction of insulin-producing pancreatic beta cells." (PMID 23282070, 2012). "Diabetes drug therapy was similar between the groups, with 63% of each group receiving oral antidiabetic drugs alone and 8% receiving insulin alone." (PMID 22762006, 2012). "We evaluated the long-term efficacy of continuous insulin infusion pump therapy (CSII) in pediatric patients with type 1 diabetes mellitus (T1DM)." (PMID 22985612, 2012). "Since our computational analyses highlighted perturbations in “insulin regulation and diabetes” gene set during exposure to SF, we proceeded to compare metabolic measures of glucose homeostasis in SF and control mice." (PMID 22629440, 2012). "Acrp30/adiponectin is known to improve insulin resistance and FGF-21 also enhances insulin sensitivity in animals and humans with diabetes." (PMID 23152772, 2012). "The advancement of diabetes treatment has gone from crude extracts of insulin and accidental discovery of sulfa-like drugs in antibiotics to the development of drugs based on improved understanding of the pathophysiology of diabetes mellitus." (PMID 23882369, 2012). "The HCPs emphasised the importance of teamwork in helping patients to control their diabetes and to advise them on insulin initiation." (PMID 22545648, 2012). "People with type 1 diabetes depend on regular insulin injections and must adhere to multiple self-care tasks to optimize glycaemic control; however, many patients struggle to self-manage their diabetes effectively." (PMID 22891794, 2012). "In a clinical setting, treatments with insulin in combination with other antidiabetic medication are shown to lower plaque load and benefit cognitive function in AD patients with diabetes." (PMID 22403710, 2012). "In particular, insulin was significantly upregulated in the rescued mice while it was downregulated in STZ-induced diabetes mice, which is comparable to one in healthy control group." (PMID 22879915, 2012). "Assessment of these parameters has revealed that type 2 diabetes mellitus and its prediabetic phase are characterised by a decrease in both glucose effectiveness and insulin sensitivity." (PMID 22698081, 2012). "The antidiabetic thiazolidinediones (TZDs) are PPAR-γ activator drugs which selective PPARγ ligands, enhance the actions of insulin in peripheral tissues, used in the treatment of type 2 diabetes mellitus to improve target cell insulin sensitivity." (PMID 22919315, 2012). "Other forms of diabetes mellitus include congenital diabetes, which is due to genetic defects of insulin secretion, cystic fibrosis-related diabetes, steroid diabetes induced by high doses of glucocorticoids, and several forms of monogenic diabetes." (PMID 22257465, 2012). "Leveraging information based on known gene product relationships allowed us to fine-map putative interactions in the enriched “insulin regulation and diabetes” module, and identify potentially important metabolic effectors induced by SF." (PMID 22629440, 2012). "Other differences observed were in age, education, and self-care behaviours (adherence to blood glucose testing recommendations and daily insulin/diabetes medications, and foot inspections)." (PMID 22857017, 2012). "Excessive protein synthesis has been demonstrated to aggravate ER stress in the pancreas, promoting accumulation of pro-insulin and apoptosis in β-cells, reducing circulating levels of insulin, and leading to the development of diabetes." (PMID 22733590, 2012). "This oxidative imbalance results in decreased insulin secretory capacity and β-cell viability, each contributing to β-cell failure and the onset of diabetes." (PMID 23226280, 2012). "For instance, problems in both the insulin secreting pancreatic islets and target tissues of insulin action are observed in diabetics, and are believed to contribute to disease pathogenesis." (PMID 23028558, 2012).
diabetes (continued). "In both men and women, diabetes cases tended to have higher BMI, waist, HbA1c, fasting glucose levels, fasting insulin levels, and FLI than controls." (PMID 23066943, 2012). "Our data show that insulin-stimulated alanine utilization was high in diabetic pigs, which fits with the general observation that gluconeogenesis from alanine is increased in diabetes." (PMID 21605349, 2011). "The results from this study suggest that, despite improvements and advances in diabetes treatment and insulin regimens, the age of menarche in adolescent females with premenarchal presentation of T1DM continues to be delayed." (PMID 21548955, 2011). "In the present study, we determined the hypoglycemic and insulin-sensitizing effects of BBR in rats with STZ-induced diabetes." (PMID 22363882, 2011). "Insulin was widely used clinically for the treatment of insulin-dependent diabetes mellitus (IDDM) or type-I diabetes." (PMID 22389858, 2011). "Inactivation of Dicer1 in adult life leads to development of diabetes due to reduced insulin expression." (PMID 22216196, 2011). "Twelve weeks of progressive endurance/strength training was effective in improving VO2max, insulin sensitivity and cardiac function in patients with type 2 diabetes mellitus." (PMID 21615922, 2011). "Together, the findings indicate that autoimmune diabetes is preceded by a state of increased metabolic demands on the islets resulting in elevated insulin secretion and suggest alternative metabolic related pathways as therapeutic targets to prevent diabetes." (PMID 22046124, 2011). "Our results implicate an inappropriate neural function of olfactory sensors following exposure to chronic levels of the hormone insulin (diabetes) or increased body weight (obesity)." (PMID 21966386, 2011). "The nearly complete normalization of the majority of diabetes-induced changes (Rescued and Prevented categories) by insulin treatment points to their regulation by insulin signalling and/or hyperglycemia." (PMID 21575160, 2011). "They established the relation between changes in right ventricle (RV) and LV insulin-stimulated glucose utilization and systolic dysfunction suggesting that diabetes affects both ventricles." (PMID 21518435, 2011). "For example, a patient with diabetes due to nelfinavir, indinavir, liponavir or saquinavir therapy will benefit more from insulin than from insulin sensitizer therapy." (PMID 21232158, 2011). "The data collected between 1991 and 1996 demonstrated that patients with type 2 diabetes mellitus exposed to sulfonylureas and exogenous insulin had significantly greater cancer-related mortality than did patients treated with metformin." (PMID 21668983, 2011). "Increased Gfap expression in Müller cells with diabetes has been described previously, and we have observed the insulin therapy–resistant induction of Gfap mRNA with diabetes." (PMID 21633715, 2011). "The proportion of subjects who developed diabetes mellitus significantly increased as the baseline fasting insulin level increased from first to fourth quartile." (PMID 22129309, 2011). "Three of the four crossing interactions occur in diabetes-related traits (glucose and insulin levels and area under the curve at 10wks), which have relatively lower genetic correlations among the traits mapped here." (PMID 21931559, 2011). "In people with type 2 diabetes (the most common form of diabetes), blood sugar control fails because the fat and muscle cells that usually respond to insulin by removing sugar from the blood become insulin resistant." (PMID 22039354, 2011). "The pre-diabetes group was more insulin resistant (p < 0.0001) as measured by homeostasis assessment model (HOMA-IR) compared to NGT group." (PMID 21219665, 2011). "In our previous study, we found that HNF4α was sensitive to plasma insulin level and was downregulated by SREBPs in hyperinsulinemia diabetes and hepatic SREBPs were downregulated by HNF4α overexpression in mice (unpublished data)." (PMID 22190905, 2011).
diabetes (continued). "In conclusion, we have demonstrated that a β-cell specific disruption of the miRNAs network, although allowing for apparently normal β-cell development, leads to progressive impairment of insulin secretion, glucose homeostasis and diabetes development." (PMID 22216196, 2011). "Women who received prenatal care, were treated with insulin during pregnancy, or completed a 6-week postpartum visit were also more likely to receive a postpartum diabetes screening." (PMID 22005617, 2011). "Complications related to the steroid treatment were minimal: among the 23 patients of the MPDN group, only one needed insulin for adequate diabetes control." (PMID 21406101, 2011). "In the treatment of diabetes during pregnancy the spotlight is often on insulin therapy; however, in recent years studies have been done that assess the impact of oral hypoglycemic agents and metformin on pregnancy outcomes." (PMID 21501437, 2011). "Hyperglycemia, the sine qua non of diabetes, results from a combination of impaired insulin secretion and impaired insulin action." (PMID 21887289, 2011). "Together, these results imply that the mice who later progress to diabetes are characterized by enhanced glucose-stimulated insulin secretion (GSIS) at an early age or that they are inappropriately insulin resistant for their degree of body weight." (PMID 22046124, 2011). "FTY720, an S1P1 modulator which has been shown to prevent diabetes in NOD mice and islet rejection, prevented loss of insulin+ cells, T cell infiltration and lymphangiogenesis, demonstrating that lymphangiogenesis is involved in islet inflammation." (PMID 22132197, 2011). "There has been limited clinical evidence to suggest that alcohol should be avoided in people with diabetes, and, in fact, some suggest moderate alcohol intake improves insulin sensitivity." (PMID 21655140, 2011). "Since the 1960s, the surgical treatment for diabetes mellitus has evolved to become a viable alternative to insulin administration, beginning with pancreatic transplantation." (PMID 22013505, 2011). "Adolescent females diagnosed pre-menarche had a longer duration of diabetes and a higher daily insulin dose per kg than the group diagnosed with T1DM after menarche." (PMID 21548955, 2011). "Over the past eight years, his diabetes had been treated with insulin by using a MiniMed Paradigm 722 insulin pump (Medtronic Inc., Northridge, CA, USA) as well as with pramlintide 15 μg three times daily prior to meals." (PMID 21722403, 2011). "Search terms used included embryonic stem cells, induced pluripotency, islet cells, insulin production, and diabetes mellitus." (PMID 21716654, 2011). "The NZO mouse is an established polygenic model for studying obesity-related diabetes as it rapidly develops symptoms of diabetes characterized by early onset obesity, insulin resistance and eventually destruction of insulin-producing pancreatic beta cells." (PMID 21554713, 2011). "The demographic data of those patients were; two cases with diabetes more than ten years under insulin control and one patient who received pre-operative radiotherapy." (PMID 21999171, 2011). "Many oral hypoglycaemic agents, such as sulfonylurea and biguanides, are available along with insulin for the treatment of diabetes mellitus, but these agents have significant side effects, and some are ineffective in chronic diabetic patients." (PMID 20981322, 2011). "In chemically or genetically obtained rat diabetes models in which maternal serum insulin depletion and hyperglycemia are induced, proliferation of inner cell mass or total cell numbers within blastocysts is inhibited." (PMID 22110471, 2011). "Before adjustment, olmesartan users were more likely to have ischemic heart disease and diabetes, utilizing more antidiabetic agents including insulin and oral hyperglycemic drugs, than candesartan users." (PMID 21827713, 2011).
diabetes (continued). "Carbohydrate restriction in conjunction with metformin and liraglutide is an effective treatment option for patients with advanced diabetes who are candidates for instituting insulin or who are in need of intensified insulin treatment." (PMID 22196251, 2011). "Dietary compliance must return to its proper place as a cornerstone of diabetes therapy, while the practice of covering dietary indiscretions with increasing doses of insulin should be discouraged." (PMID 21668983, 2011). "Strikingly, 100% of RIP-Cre Dicer1Δ/Δ mice developed diabetes by 25 weeks of age indicating the importance of the miRNAs network for the proper function of insulin-producing cells and, in turn, for glucose metabolism." (PMID 22216196, 2011). "Treatment of diabetes mellitus mainly revolves around conventional oral hypoglycaemic agents and insulin replacement therapy." (PMID 21747828, 2011). "Adiponectin is an adipocyte-secreted cytokine, which has insulin sensitizing, anti-inflammatory, and anti-atherosclerotic properties, and is decreased in persons that are obese and have diabetes." (PMID 21663637, 2011). "The involvement of insulin signaling in AD has led to the proposal that this neurodegenerative disorder is a “special form of diabetes mellitus of the brain”." (PMID 21731631, 2011). "Diabetes was identified in 1,214 participants by self report, self-reported use of insulin or oral medications for diabetes, or fasting glucose ≥6.99 mmol/L (126 mg/dL)." (PMID 21496321, 2011). "Resistance to insulin in skeletal muscle and impaired insulin stimulated glucose uptake is a prominent feature of type 2 diabetes mellitus." (PMID 22114711, 2011). "Delayed wound healing in diabetes not only reduces insulin sensitivity and the occurrence of glycosylation of various proteins, enzymes, and insulin caused by hyperglycaemia, but also raises oxidative stress and decreases antioxidant defense systems." (PMID 22088091, 2011). "As observed in the microarray analysis, the majority of diabetes-induced changes were normalized with insulin treatment." (PMID 21575160, 2011). "Type 2 diabetes mellitus results from a combination of insulin resistance, defects in insulin secretion and hyperglucagonemia." (PMID 22140505, 2011). "The benefit of the trans-vessel wall technique should be greatest in transplantations involving cells with limited capability of performing diapedesis, for example when transplanting insulin-producing cells in diabetes mellitus." (PMID 21858072, 2011). "UPI offspring develop diabetes in later life with a phenotype that is similar to that observed in T2D humans with alterations in insulin secretion and action and a failure of beta-cell function and growth." (PMID 22110471, 2011). "Treatment with either insulin or ozone therapy significantly reversed the effects of diabetes mellitus." (PMID 22185664, 2011). "Structural and non-structural proteins of HCV modulate cellular gene expression in such a way that insulin signaling is hampered, concomitantly leads toward diabetes mellitus." (PMID 22008087, 2011). "Analysis of nursing records showed that patients with diabetes preserved their ability to take their own decisions about insulin doses." (PMID 22007324, 2011). "Sox4 reportedly has a role in insulin secretion in the adult β-cell downstream of the KATP channel, and is identified as a risk factor for diabetes and obesity." (PMID 21362171, 2011). "Impaired insulin signaling and GLUT4-translocation in peripheral tissues is a major hallmark in diabetes." (PMID 21818330, 2011). "Four days after insulin treatment was started, her ulcer had healed and she was discharged from the hospital and follow-up was conducted at her local diabetes clinic." (PMID 22051138, 2011). "It is postulated to induce diabetes by the degeneration and necrosis of β cells of islet of langerhans of pancreas, which leads to the reduction in insulin release." (PMID 22363893, 2011).